HK2 (hexokinase 2)
Diseases named in the same sentence as HK2 in open-access papers (continued):
Sharing a sentence is not in itself a finding about the gene and the disease.
Lung Squamous Cell Carcinoma (3 papers, 2017 to 2025). "Lung squamous cell carcinoma (LUSC) represents a glycolysis‐predominant subtype, characterized by high expression levels of glucose transporter 1 (GLUT1), hexokinase 2 (HK2), and lactate dehydrogenase A (LDHA), as well as strong FDG uptake on PET imaging." (PMID 41163383, 2025). "Both HK2 and LCN2 expressions significantly increased in cancer tissues when compared with normal tissues in lung squamous cell carcinoma." (PMID 29285270, 2017). "From TGCA database and immunohistochemistry analysis, HK2 and LCN2 expression increased in lung squamous cell carcinoma and their related adjacent normal tissues." (PMID 29285270, 2017).
oligodendroglioma (3 papers, 2016 to 2025). A well-differentiated (WHO grade II), diffusely infiltrating neuroglial tumor, typically located in the cerebral hemispheres. "Astrocytomas, for instance, exhibited elevated levels of glycolysis-related proteins such as hexokinase 2, lactate dehydrogenase A (LDHA), and glucose-6-phosphate dehydrogenase compared to oligodendrogliomas." (PMID 39996200, 2025).
pancreatic ductal adenocarcinoma (3 papers, 2019 to 2023). An infiltrating adenocarcinoma that arises from the epithelial cells of the pancreas. "HK2 affects the invasion potential of pancreatic ductal adenocarcinoma (PDAC) cells by directly regulating glycolysis, and HK2 promotes the disease progression of PDAC by regulating lactate production." (PMID 37539493, 2023).
retinal degeneration (3 papers, 2022 to 2023). Degeneration of the retina. "Compared to other models of retinal degeneration (e.g., rd1, rd10), the PR degeneration in dcKO animals is slower, suggesting that HK1 and PKM1 can partially compensate for the loss of HK2 and PKM2." (PMID 37626853, 2023). "Another study reported that the selective knockdown of HK2 in rods leads to age-related photoreceptor degeneration and retinal metabolic remodelling, rendering HK2 a potential target for the treatment of retinal degeneration." (PMID 35624805, 2022). "Concerning DP, MBD2 was involved in the formation of the eye, interacting both with HK2 and HIF1A, while PIWIL4 displayed an interaction with DICER1, which was involved in retinal degeneration." (PMID 37359372, 2023).
urothelial carcinoma (3 papers, 2019 to 2025). A malignant neoplasm derived from the transitional epithelium of the urinary tract (urinary bladder, ureter, urethra, or renal pelvis). "Studies have found that HK2 expression in urothelial carcinoma and NSCLC cells is suppressed by SLC14A1." (PMID 41301792, 2025).
acute kidney injury (2 papers, 2022 to 2024). Sudden and sustained deterioration of the kidney function characterized by decreased glomerular filtration rate, increased serum creatinine or oliguria. "In acute kidney injury (AKI), the increased HK-2 expression and lactate production further upregulate HK-2, with AST-120 being shown to ameliorate AKI via downregulating HK-2 and reducing H3K18 lactylation." (PMID 39683818, 2024).
acute lymphoblastic leukemia (2 papers, 2018 to 2021). Leukemia with an acute onset, characterized by the presence of lymphoblasts in the bone marrow and the peripheral blood. "For example, HK2 deficiency has been shown to decrease tumor burden in a mouse model of T cell acute lymphoblastic leukemia (T-ALL)." (PMID 30140438, 2018). "Co-administration of glucocorticoids with inhibitors of HK2, such as 3-bromopyruvate, increased in vitro sensitivity of glucocorticoids in acute lymphoblastic leukemia (ALL)." (PMID 34680164, 2021).
adenoma (2 papers, 2019 to 2023). A neoplasm arising from the epithelium. "Indeed, the HK2 and Scl2a1/Glut1 genes were both significantly up-regulated in each IKKαKO urethane-induced large adenoma as compared with multiple IKKαWT controls." (PMID 31792060, 2019). "In two previous studies, the expression of GLUT1, HK2, MCT4, and CA-IX and the Ki-67 proliferation index were higher in Hürthle cell thyroid carcinoma and adenoma as compared to their non-oncocytic counterparts." (PMID 36253663, 2023).
age-related macular degeneration (2 papers, 2021 to 2023). Age-related loss of vision in the central portion of the retina (macula), secondary to retinal degeneration. "A recent study showed that photoreceptors of individuals with age-related macular degeneration (AMD) display increased expression of two key glycolytic enzymes, HK2 and PKM2, indicating that AMD is associated with a glucose shortage." (PMID 36896135, 2023).
Alzheimer disease (2 papers, 2022 to 2025). A progressive, neurodegenerative disease characterized by loss of function and death of nerve cells in several areas of the brain leading to loss of cognitive function such as memory and language. "In the development of Alzheimer's disease (AD), HK2 localization to mitochondria is disrupted by Aβ aggregates, which impairs microglial phagocytosis and promotes neuroinflammation." (PMID 41254936, 2025).
benign glioma (2 papers, 2021 to 2022). "Furthermore, high levels of HK2 are correlated with high levels of COL5A1 in patients with GBM relative to benign glioma." (PMID 35158782, 2022). "High levels of NOX2 are correlated with high levels of HK2 and glucose uptake in patients with GBM relative to benign glioma." (PMID 35158782, 2022).
bladder tumor (2 papers, 2022 to 2024). "By analyzing the human bladder tumors, we observed a clear trend toward an increased mRNA level of the glycolytic genes GLUT1 and HK2, compared to their healthy counterparts, while the mitochondrial marker PGC-1α was downregulated." (PMID 36233054, 2022).
Burkitt lymphoma (2 papers, 2013 to 2015). A rare form of malignant mature B-cell non-Hodgkin lymphoma. "It is known that the hypoxia-inducible factor 1-alpha (HIF1A) and MYC proteins cooperatively regulate expression of the HK2 and PDK1 genes, respectively, in the Burkitt lymphoma (BL) cell line P493-6, carrying an inducible MYC gene repression system." (PMID 26312753, 2015). "Relevant to the present results, selective induction of HK2 and pyruvate dehydrogenase kinase-1 (PDK1) by hypoxia (and HIF-1α and c-myc) was observed in a previous study of human P493-6 B-lymphoblastoid cells, a model for human Burkitt’s lymphoma." (PMID 23866118, 2013).
cardiomyopathy (2 papers, 2020 to 2021). A disease of the heart muscle or myocardium proper. "In cardiomyopathy, glycogen synthase kinase 3 beta (GSK3β)-induced HK2 dephosphorylation can cause mitochondrial HK2 liberation, indicating that an altered HK2 activity is a key factor for mitochondrial HK2 expression and translocation." (PMID 34741026, 2021). "We examined the expressions of miR-143 targets that are known to be involved in cardiomyopathy or cardiac remodeling and observed that hexokinase 2 (HK2) expression was drastically lower in the transgenic hearts." (PMID 32855642, 2020). "We further evaluated the protein expression of 5 miR-143 targets (HK2, ERK5, IGF1R, IGFBP5 and ORP8) that have been shown to be involved in cardiomyopathy or cardiac remodeling." (PMID 32855642, 2020).
chronic lymphocytic leukemia (2 papers, 2019 to 2023). "CDK7 may promote HIF1α transcriptional activity in chronic lymphocytic leukemia cell lines, and the expression of GLUT1, GLUT3, Hexokinase 1, and Hexokinase 2 is regulated by HIF1α43,44." (PMID 31784510, 2019).
clear cell renal cell carcinoma (2 papers, 2020 to 2021). "ARNT was recently found upregulated in clear cell renal cell carcinoma: its expression was responsible for cell migration/invasion and, coherently with our data also for the regulation of glycolytic enzymes like PFKFB3, (6−phosphofructo−2−kinase/fructose−2,6−bisphosphatase 3) and HK2 (hexokinase-2)." (PMID 35251951, 2021).
cystic kidneys (2 papers, 2016 to 2024). "Using microarray analysis and qPCR, we found an upregulation of genes involved in glycolysis (Hk1, Hk2, Ldha) and a downregulation of genes involved in gluconeogenesis (G6pc, Lbp1) in cystic kidneys of Cy/+ rats compared with wild-type (+/+) rats." (PMID 26752072, 2016). "In addition, enzymes for irreversible steps of glycolysis were upregulated in renal cysts, including hexokinase 1 and 2 (HK1, 1.7×; HK2, 6.2×), and pyruvate kinase (PKM, 1.6×)." (PMID 39000280, 2024).
depression (2 papers, 2024 to 2026). "By prioritizing UCP2, SOD1, HK2, NDUFS4, and NEU1, our findings highlight novel, immune-mediated pathways in depression and nominate promising targets for future diagnosis and therapeutic intervention." (PMID 41601681, 2026).
diabetic nephropathy (2 papers, 2022). "The glycolysis-associated genes HK2 and LDHA were upregulated in the diabetic kidney organoids, whereas PGC1α (a key regulator of mitochondrial biogenesis involved in diabetic nephropathy) was downregulated." (PMID 35561674, 2022).
endometriosis (2 papers, 2022 to 2025). The growth of functional endometrial tissue in anatomic sites outside the uterine body. "In endometriosis models, IGF2BP1 knockdown decreased the expression of key glycolytic enzymes, including PKM2 and HK2, and reduced glucose uptake, highlighting IGF2BP1's role in supporting metabolic reprogramming through PKM2 regulation." (PMID 41210679, 2025).
fibrosis (2 papers, 2025). the formation of excess fibrous connective tissue in an organ or tissue in a reparative or reactive process. "These insights highlight ALA’s therapeutic potential by inhibiting lung fibroblast activation via TGF-β1 and autophagy proteins (Parkin/LC3) while counteracting metabolic reprogramming in bleomycin-induced fibrosis by suppressing HK2, PFKFB3, Parkin, and LC3 activation." (PMID 40868211, 2025).
germ cell tumor (2 papers, 2019 to 2022). A benign or malignant, gonadal or extragonadal neoplasm that originates from germ cells. "For example, although increased Hk2 expression is associated with a more aggressive phenotype in testicular germ cell tumors, overall Hk2 expression is reduced in such tumors relative to paired normal testicular tissues." (PMID 35235554, 2022).
Glucose intolerance (2 papers, 2023 to 2024). Glucose intolerance (GI) can be defined as dysglycemia that comprises both prediabetes and diabetes. "Loss of adipose HK2 leads to reduced glucose disposal by adipose tissue and increased glucose production in liver, ultimately causing glucose intolerance." (PMID 36920797, 2023). "Loss of adipose HK2 is sufficient to cause glucose intolerance, in two ways." (PMID 36920797, 2023). "Is the reduction in HK2 in obese mice and patients sufficient to contribute to systemic insulin insensitivity and glucose intolerance?" (PMID 36920797, 2023). "Thus, loss of adipose HK2 non-cell-autonomously promotes glucose intolerance by enhancing hepatic glucose production." (PMID 36920797, 2023). "Moreover, glucose intolerance was observed in adipose-specific heterozygous Hk2 knockout mice." (PMID 36920797, 2023).
hematoma (2 papers, 2023 to 2026). A hematoma is a collection of blood from a vascular structure into an extravascular space. "Both the hematoma-surrounding region and contralateral hemisphere showed substantially diminished signals for Hspa5, Hk2, and Tnf compared to earlier timepoints, with expression levels dropping to or below naive baseline values." (PMID 41601478, 2026).
Hypertension (2 papers, 2024). The presence of chronic increased pressure in the systemic arterial system. "Among these genes, PKM and LEP were overexpressed in women older than 35 years old ( p<0.05; p<0.05); the expression of PKM, LEP, and HK2 differed remarkably in women with different BMI (all p<0.05); PKM overexpressed in women with hypertension (p<0.05)." (PMID 38166707, 2024).
inflammatory bowel disease (2 papers, 2022 to 2024). A spectrum of small and large bowel inflammatory diseases of unknown etiology. "We examined the relationship between HK2 expression and inflammation severity using bulk transcriptome data derived from the mucosa of thoroughly phenotyped inflammatory bowel disease (IBD) patients of two independent cohorts including both subtypes Crohn’s disease (CD) and ulcerative colitis (UC)." (PMID 39444028, 2024).
intrahepatic cholangiocarcinoma (2 papers, 2023 to 2025). A carcinoma that arises from the intrahepatic bile duct epithelium in any site of the intrahepatic biliary tree. "FGFR2 inhibition in patient-derived intrahepatic cholangiocarcinoma (ICC) cell lines containing an overactive FGFR2 mutant decreases HK2, PKM2, and LDHA expression." (PMID 39433211, 2025).
kidney (2 papers, 2015 to 2023). "Here, we found that HK2-mediated mitophagy alleviates hypoxia-induced kidney injury, implying that HK2 confers cellular protection during the pathophysiology of hypoxic kidney diseases by integrating energy metabolism and mitophagy." (PMID 37225700, 2023).
liver cirrhosis (2 papers, 2022 to 2025). "According to previous research, increased levels of Hexokinase 2 (HK2) are associated with renal damage, that supports our results that alcohol and acetaminophen-induced liver cirrhosis damages the kidneys." (PMID 40271532, 2025).
myeloid leukemia (2 papers, 2019 to 2020). A clonal proliferation of myeloid cells and their precursors in the bone marrow, peripheral blood, and spleen. "In this study, we showed that matrine significantly inhibited the cell proliferation and induced apoptosis by regulating Warburg effect through controlling hexokinases 2 (HK2) expression in myeloid leukemia cells." (PMID 31607919, 2019). "Taken together, these results suggest that matrine can synergize with pharmacological inhibitor of HK2 against human myeloid leukemia cells." (PMID 31607919, 2019). "We further demonstrated that matrine could synergize with lonidamine, an inhibitor of HK2, for the treatment of myeloid leukemia, both in vitro and in vivo." (PMID 31607919, 2019). "Taken together, our findings reveal that matrine could promote human myeloid leukemia cells apoptosis via regulating Warburg effect by controlling HK2." (PMID 31607919, 2019). "Furthermore, we showed that matrine could synergize with HK2 inhibitor lonidamine for confronting human myeloid leukemia." (PMID 31607919, 2019). "Given that knockdown of HK2 promotes matrine-induced cell apoptosis and growth inhibition, we examined whether or not pharmacological inhibition of HK2 could sensitize human myeloid leukemia cells to matrine challenge." (PMID 31607919, 2019).
myopia (2 papers, 2023 to 2026). "Additionally, we assessed the role of glycolysis in myopia by overexpressing HK2 and using 2-deoxy-d-glucose (2DG)." (PMID 41980459, 2026). "This may explain why ROS induced in photoreceptors further upregulated the expression of myopic molecular marker (MMP2) in co‐cultured RPE cells in our study, and therefore indicate how HK2‐related glucose metabolism might be related to high myopia development." (PMID 37746666, 2023).
neuroendocrine tumor (2 papers, 2013 to 2023). "Using real-time PCR, gene expression of GLUT1, HK1 and HK2 were studied in 34 neuroendocrine tumors (NETs) in comparison with 14 colorectal adenocarcinomas (CRAs)." (PMID 26824929, 2013).
Pan (2 papers, 2021 to 2022). "Additionally, the expression of the glycolysis rate-limiting genes HK2, PFKP and PKM2 showed expression patterns similar to non-rate-limiting genes in the Pan Cancer TCGA cohort." (PMID 36505421, 2022).
Parkinson disease (2 papers, 2025 to 2026). A progressive degenerative disorder of the central nervous system characterized by loss of dopamine producing neurons in the substantia nigra and the presence of Lewy bodies in the substantia nigra and locus coeruleus. "In the development of Parkinson's disease (PD), HK2‐mediated glycolysis exacerbates neuronal damage under rotenone stress, and its inhibition by compounds like gastrodin rescues cell viability." (PMID 41254936, 2025).
periodontitis (2 papers, 2023 to 2025). An acute or chronic inflammatory process that affects the tissues that surround and support the teeth. "Although we presented data showing that inflammatory responses to P. gingivalis are inhibited with the inhibition of HK2, an animal model should be utilized in order to determine whether the modulation of HK2 expression can reduce the progression of periodontitis." (PMID 36793034, 2023).
prostate adenocarcinoma (2 papers, 2018 to 2022). "A complete biodistribution study of [225Ac]hu11B6 was performed in a genetically modified mouse model (Hi-Myc x pb_KLK2) that has prostate specific expression of human hK2 (pb_KLK2) and spontaneous development of prostate adenocarcinoma (Hi-Myc) at 20–30 weeks of age." (PMID 29691406, 2018).
schizophrenia (2 papers, 2018 to 2024). A major psychotic disorder characterized by abnormalities in the perception or expression of reality. "MiR-143 is a critical miRNA involved in schizophrenia development by targeting some major genes contributing to the onset of schizophrenia, including ERK5, ERBB3, HK2, and PKCε." (PMID 39058106, 2024). "This variation could have biological relevance when both HK2 and HK3 elements are expressed, such as in ALS and schizophrenia." (PMID 30072963, 2018).
serous carcinomas (2 papers, 2018 to 2021). "The glycolytic enzyme HK2 is higher in EOC tissues than in normal ovarian tissues, in advanced stages, and serous carcinomas than in non-serous carcinomas." (PMID 35054401, 2021).
skin cancer (2 papers, 2020 to 2024). "HK2 triggers programmed cell death and cellular self-digestion in skin cancer cells." (PMID 39224810, 2024).
tongue cancer (2 papers, 2017 to 2022). A malignant neoplasm affecting the tongue. "It has been reported that EGCG also inhibits the expression of hexokinase 2 (HK2), one of the rate limiting enzyme of the aerobic glycolysis, partially through the down-regulation of Akt signaling pathway in human tongue carcinoma." (PMID 28611670, 2017).
vitiligo (2 papers, 2017 to 2025). Generalized well circumscribed patches of leukoderma that are generally distributed over symmetric body locations and is due to autoimmune destruction of melanocytes. "As a compensatory mechanism for energy production, some glycolytic enzymes (hexokinase 2, HK2; pyruvate dehydrogenase kinase 1, PDHK1; pyruvate kinase M2, PKM2) are upmodulated in vitiligo melanocytes." (PMID 41007740, 2025).
Zinc deficiency (2 papers, 2017 to 2025). A deficiency of the essential metal Zinc; an essential cofactor for many enzymes. "Further research revealed that zinc deficiency reprograms glucose metabolism, supporting aberrant cell proliferation by modulating the expression of miR-143 and its target, hexokinase 2 (HK2)." (PMID 40933952, 2025). "In zinc-deficiency (ZD)-associated esophageal neoplasia, ZD modulats miR-143 expression and its target HK2." (PMID 29156804, 2017).
acute promyelocytic leukemia (1 paper, 2025). An aggressive form of acute myeloid leukemia (AML), characterized by arrest of leukocyte differentiation at the promyelocyte stage, due to a specific chromosomal translocation t(15;17) in myeloid cells. "Arsenic trioxide (As2O3), an established therapeutic agent for acute promyelocytic leukemia (APL), has also been shown to inhibit HK2 expression and glycolysis in cancer cells." (PMID 40735327, 2025).
adrenocortical carcinoma (1 paper, 2022). "We further evaluated the expression of HK2 between the normal tissues and tumor tissues of ACC (Adrenocortical carcinoma), LGG (Brain lower grade glioma), THYM (Thymoma), and UCS (Uterine carcinosarcoma) (p < 0.01) with GTEx dataset as a complement of TIMER2 database." (PMID 36335239, 2022).
alcoholic liver diseases (1 paper, 2023). A disorder caused by damage to the liver parenchyma due to alcohol consumption. "HK2 protein abundance in liver tissues was reduced in mice with alcoholic liver disease, which was rescued by ZNF281 knockdown." (PMID 36514923, 2023).